TNF (tumor necrosis factor)
Diseases named in the same sentence as TNF in open-access papers (continued):
Sharing a sentence is not in itself a finding about the gene and the disease.
psoriasis (continued). "These cultures were treated with a combination of 20 ng/ml IL-17A and 10 ng/ml TNF-α to model some of the inflammatory processes seen in psoriasis skin." (PMID 30321197, 2018). "Inflammatory cytokines involved in development of insulin resistance, such as TNF-α, IL-6 together with leptin and adiponectin, were also found in psoriasis." (PMID 30011841, 2018). "Paradoxical psoriasis regressed in all patients when anti-TNF therapy was discontinued, but relapsed or persisted in 7 of 11 cases (64%) when anti-TNF treatment resumed." (PMID 29295985, 2018). "Previous studies have also shown psoriasis macrophages to secrete increased IL-8, IL-1α/β, and TNFα when untreated and this is in agreement with our findings." (PMID 29535706, 2018). "Our design is aimed at retaining the anti-TNF-α and anti-ILs pharmacological profiles from thalidomide and to enhance the efficacy against specific cytokines related to psoriasis." (PMID 30301277, 2018). "The same neutralizing strategy led to an amelioration of the psoriasiform phenotype in IL-17C transgenic mice, pointing toward a possible role of the TNF/IL-17C axis in psoriasis." (PMID 30127781, 2018). "Severe inflammatory skin diseases like severe psoriasis are often treated with biologics, which target the proinflammatory cytokine signaling pathways of TNFα, IL-23 and IL-17." (PMID 29968819, 2018). "In fact, lupus-like syndrome can be observed in 0.5–1% of anti-TNF treated patients and 2–5% of patients develop psoriasis-like skin lesions, called paradoxical psoriasis." (PMID 30555460, 2018). "The current generation of biologic agents target cytokines critical to the pathogenesis of psoriasis, including the three known major drivers: TNF-α, IL-23, and IL-17." (PMID 29910818, 2018). "Yet, the arrival of TNF blockers in the early 2000s completely revolutionised the management of psoriasis and other chronic inflammatory diseases." (PMID 30555460, 2018). "We initially studied the impact of tofacitinib on intracellular pathways activated in human keratinocytes by proinflammatory cytokines with a pathogenic role in psoriasis, including IFN-γ, IL-22, TNF-α, and IL-17." (PMID 30581877, 2018). "In skin lesions of psoriasis patients, CD11c+ inflammatory DC can be detected more frequently, expressing TNFα, IL-23, and iNOS (so-called TNFα- and iNOS-expressing TIP-DC)." (PMID 29963046, 2018). "The pathogenesis of paradoxical psoriasis in patients receiving anti-TNF treatments for classical psoriasis is unclear." (PMID 29295985, 2018). "IL-17, in cooperation with other cytokines such as TNFα and IL-22, induces the development of the psoriasis phenotype through tissue cell activation." (PMID 29316717, 2018). "Similar to IL-23, psoriasis macrophages had higher basal expression levels and secreted significantly more TNFα when stimulated with IL-36γ." (PMID 29535706, 2018). "Subsequent to the deregulation of NF-κB and related proteins, a decrease in the expression levels of TNF-α, IL-17, and IL-23 took place, further strengthening the utilization of piclidenoson as a drug candidate to combat psoriasis." (PMID 29862305, 2018). "We found that IL‐35 recombinant protein was able to reach comparable results as the TNF‐α monoclonal antibody did in regard to the treatment of psoriasis." (PMID 29193791, 2018). "Mean duration of anti-TNF treatment until onset of paradoxical psoriasis was 9.5 months (range 3 weeks to 5 years)." (PMID 29295985, 2018). "Monoclonal antibodies against TNF-α, IL-17, and IL-23 were found to mediate a strong anti-inflammatory effect that has been already implemented for the treatment of psoriasis patients and proved to be highly efficacious." (PMID 29862305, 2018). "The involvement of these cytokines in psoriasis has also been revealed through the therapeutic silencing of key immune system components, such as TNF-α, IL-17, IFN-γ, IL-22, and the Th17/IL-23 axis." (PMID 29679037, 2018).
psoriasis (continued). "On the other hand, IL-6 promotes the production of T helper (Th) 17 cells and, together with TNF-α, plays a central role in the development of psoriasis lesions." (PMID 29619128, 2018). "The pathogenesis of psoriasis was initially proposed to rely on Th1 responses, based on the identification of elevated expression of Th1 cytokines, such as IFNγ, TNFα, and IL-12, in the lesion." (PMID 30127781, 2018). "These pro-inflammatory effects of TNF are corroborated in psoriasis, where TNF is found to dictate the inflammatory environment in several ways." (PMID 30555460, 2018). "Psoriasis patients’ monocytes showed increased adherence to both untreated and TNFα activated HUVECs." (PMID 29535706, 2018). "Biologics targeting TNF-α and IL-17A have been developed and found to be very effective for managing psoriasis." (PMID 30321197, 2018). "T-cell-depleted mice treated with anti-TNF developed a psoriasis-like phenotype with increased acanthosis that was similar to non-depleted control mice treated with anti-TNF." (PMID 29295985, 2018). "In psoriasis, TNF-α is thought to work synergistically with IL-17A by inducing IL-17 receptor (IL-17R) expression on keratinocytes, promoting the maturation of Th17 and Th22 cells, and increasing the production of IL-17A31." (PMID 30054515, 2018). "A greater proportion of psoriasis patients with self-reported PsA used biologics, particularly tumor necrosis factor inhibitors, compared with patients with psoriasis only." (PMID 30886979, 2018). "Altogether, besides IL-1β and TNF-α, C5a is likely to play a role in the early neutrophil predominant and auto-inflammatory phase of psoriasis." (PMID 29713318, 2018). "The role of inflammation and cytokines in psoriasis is well defined; however, only a few, cytokines particularly TNF-α, have reached significant levels in clinical trials." (PMID 29538330, 2018). "TNF-α constitutes a landmark mediator in the pathogenesis of psoriasis since it is the first cytokine to be successfully targeted by therapeutic monoclonal antibodies or fusion proteins for the treatment of the disease." (PMID 29316717, 2018). "Among bDMARDs, most data concern TNF antagonists: in HCV patients with psoriasis, their use appears safe, although sporadic cases of hepatocellular carcinoma (HCC) have been reported." (PMID 29546055, 2018). "An intriguing question is why anti-TNF is able to induce a psoriatic phenotype in wild-type mice and enhance type I IFN production by pDCs from blood of healthy donors, but only 2–5% of anti-TNF-treated patients develop paradoxical psoriasis." (PMID 29295985, 2018). "Psoriatic lesions are highly infiltrated with immune cells, and pro‐inflammatory cytokines produced by these cells such as TNF‐α, IL‐17 and IL23 have been linked to the pathogenesis of psoriasis." (PMID 29193791, 2018). "Since the late 1990s, TNF-inhibitors (TNFi), in particular adalimumab, etanercept and infliximab, have become a cornerstone in the treatment of psoriasis." (PMID 29751529, 2018). "High quality of evidence was found favoring use of anti-TNF (etanercept) treatment for pediatric psoriasis and use of combined therapy of steroids plus vitamin D rather than vitamin D alone." (PMID 30133547, 2018). "Stimulated by activated macrophages in adipose tissue, adipocytes secrete adipokines such as IL-6, TNF-α, visfatin and leptin, which also play an important role in the pathogenesis of psoriasis." (PMID 29696068, 2018). "Alternatively, in psoriasis, TNF is a major cytokine that acts on the IL-23/Type 17 T-cell pathway at two points." (PMID 30828428, 2018). "In particular, anti-TNF-α agents seem to reduce these events in psoriasis patients whereas anti-IL-12/23 agents related CV events reduction still remain to clarify." (PMID 30150978, 2018). "The authors found significantly higher levels of IFN-γ, TNF-α, IL-6, IL-8, IL-12, and IL-18 in patients with psoriasis." (PMID 29619128, 2018).
psoriasis (continued). "Intracellular signals for many of the cytokines elevated in psoriasis lesions, including TNF and IL-17A, are transduced though the MAP kinase and NF-κB pathways." (PMID 30321197, 2018). "Increases in CD8+ T cell derived TNF-α and IL-17A also intriguing as psoriasis has traditionally been thought of as a Th1/Th17 mediated disease." (PMID 30054515, 2018). "It is aggravated by the presence of TNF-α, a key proinflammatory cytokine in the pathogenesis of psoriasis, and vice versa it can lead to unfavorable long term prognosis of psoriasis patient." (PMID 30011841, 2018). "Cytokine production by DC plays a significant role in the pathology of psoriasis: TNFα contributes to inflammation in the skin, while IL-12 and IL-23 instruct T cell polarisation towards the pro-inflammatory Th1 and Th17 phenotypes, respectively." (PMID 29980703, 2018). "These skin manifestations are called “paradoxical psoriasis”, as TNF blockade is usually highly efficacious in psoriasis treatment." (PMID 29295985, 2018). "In previous studies, slanMo were identified as a subset of TNF-α- and iNOS-expressing inflammatory dermal DCs in psoriasis, so called TIP-DCs." (PMID 29977237, 2018). "Th17 cells in psoriasis release different cytokines such as IL-17, IL-22, and TNF-α and are also involved in macrophage-dependent and -independent stimulation of dendritic cells (DCs) to propagate the inflammatory response." (PMID 29910818, 2018). "IL-23/IL-17/IL-22 axes produced by abnormal activation of Th17 cells play key roles in pathogenesis of psoriasis that stimulate keratinocyte proliferation and secretion of other inflammatory cytokines such as TNF-α, IL-1, IL-6, and IL-8." (PMID 29046044, 2017). "Although the prior reports show QF conversion rate to be between 7%~ 18% in TNF-blockers users in psoriasis, the 7.3% percent is still lower than the experience of TNF blockers for psoriasis in Taiwan." (PMID 28886099, 2017). "Tumor necrosis factor-α antagonists represent a major therapeutic advance for the management of chronic inflammatory diseases, such as psoriasis." (PMID 28179019, 2017). "Using a bioinformatics approach of human skin and vascular tissue, we determined IFN-γ and TNF-α are the dominant pro-inflammatory signals linking atherosclerosis and psoriasis." (PMID 29062018, 2017). "The potential biological mechanisms that link psoriasis and metabolic syndrome are chronic Th1- and Th17-mediated inflammation with dysregulation of cytokines, including tumor necrosis factor α (TNF-α) and interleukin 6 (IL-6)." (PMID 28496169, 2017). "Physicians have much experience with the TNF blockers (infliximab and etanercept) in patients with psoriasis in preventing the development of cardiovascular events." (PMID 28103807, 2017). "DCs generate multiple proinflammatory cytokines, including TNF-α, IL-1β, IL-6, and IL-23, that promote the development of psoriasis." (PMID 28894754, 2017). "While TNF-α induced the activation of FoxO1 in human fibroblasts, the TNF-α antagonist etanercept was reported to re-activate FoxO1 in patients suffering from psoriasis." (PMID 28098832, 2017). "As the key cytokines in the pathogenesis of psoriasis, IL-17A can synergize with TNF-α to induce the production of MCP-1, IL-8, and MMP-1 by dermal fibroblasts." (PMID 28217129, 2017). "Our data showed that serum from psoriasis patients or TNF-α promoted the protein expression of CCL17 and CCL22 in HUVECs while serum from normal in culture medium silenced the expression of these chemokines." (PMID 29066845, 2017). "Serial QFT tests have revealed annual seroconversion rate between 7%~ 18% in TNF-blockers users in psoriasis, and it was 14.29% in Taiwan." (PMID 28886099, 2017). "Especially interesting is apremilast (brand name Otezla), a tumor necrosis factor-α (TNF-α) inhibitor used for the treatment of psoriasis, psoriatic dermatitis and other inflammatory diseases related to the immune system." (PMID 28845187, 2017).
psoriasis (continued). "The TNF-α antagonists adalimumab, etanercept, and infliximab have demonstrated strong efficacy in the treatment of moderate to severe psoriasis." (PMID 28894754, 2017). "In a six-month prospective study, 29 patients with moderate to severe psoriasis exhibited improvement of endothelial function and arterial stiffness following anti-TNF therapy with adalimumab." (PMID 29295598, 2017). "IL-17A and TNF-α play key roles in the complex inflammatory network of psoriasis, promoting immune activation, and the maintenance of psoriasis lesions." (PMID 28217129, 2017). "The common biotherapies for the treatment of psoriasis include monoclonal antibody against interleukin IL-12 and IL-23 (ustekinumab) and anti-cytokine therapies (e.g., anti-tumor necrosis factor (TNF) therapies (adalimumab, etanercept, and infliximab))." (PMID 29292715, 2017). "Together, these results implied that TNF-α derived from the serum of psoriasis patients has the potential to induce chemokines from endothelial cells." (PMID 29066845, 2017). "Although the in vitro data indicated that EKC increased TNF-α production, the clinical data from patients with psoriasis demonstrated a spectacular improvement with an IL-17 blockade rather than increased TNF." (PMID 28761880, 2017). "These analyses support that IFN-γ and TNF-α strongly contribute to the link between active psoriasis and atherosclerosis." (PMID 29062018, 2017). "Increased TNF-α levels are found in various chronic inflammatory disorders including psoriasis, psoriatic arthritis and rheumatoid arthritis." (PMID 29232931, 2017). "Our patient was also administered the TNF-α blocker adalimumab for psoriasis prior to rituximab therapy." (PMID 28182165, 2017). "Here we provide both in vitro data and unbiased bioinformatic analyses to provide evidence for the involvement of two pro-inflammatory cytokines, IFN-γ and TNF-α, as key factors connecting inflammation in psoriasis and atherosclerosis." (PMID 29062018, 2017). "In recent years, targeting cytokines has become very popular for the treatment of severe psoriasis, with modalities targeting TNFα, IL-12, and, most recently, IL-1722–25." (PMID 28894119, 2017). "The latest published meta-analysis on the effect of TNF inhibitors on cardiovascular events has included 49,795 patients with psoriasis and/or PsA from five studies." (PMID 29295598, 2017). "Treatment of psoriasis patients with TNF-α inhibitors has been shown to suppress serum leptin levels." (PMID 29065479, 2017). "The paradigm for psoriasis treatment has also shifted to targeting more specific cytokines such as TNF-α, IL-17 and IL-23." (PMID 29232931, 2017). "Our previous research demonstrated that the expression of CKLF1, induced by TNF-α or psoriasis serum in human umbilical vein endothelial cells (HUVECs), increased in psoriatic lesions." (PMID 29066845, 2017). "NHEK were stimulated by A-SAA or the cytokines IL-1α, IL-17A, IL-22, OSM, TNF-α alone or in combination, previously reported to reproduce features of psoriasis." (PMID 28708859, 2017). "The role of TNF-α, IL-17 and IL-1β in psoriasis pathogenesis has been well documented, being a particularly effective strategy to block their production." (PMID 29295585, 2017). "Infliximab, a chimeric monoclonal antibody that neutralizes both soluble and membrane-bound TNF-α, is an effective treatment in autoimmune diseases such as psoriasis, RA and IBD, which can lead to long-term remission." (PMID 29250057, 2017). "Available evidence suggests that patients who developed secondary psoriasis during the course of anti-TNF treatment for IBD should probably continue the therapy." (PMID 28905102, 2017). "TNF-α is a key cytokine in the development of psoriasis, and most psoriatic patients have a positive response to the anti-TNF biologics." (PMID 28217129, 2017).
psoriasis (continued). "BMDCs were generated as described in the Materials and Methods, and the BMDCs were activated with TNF-α (20 μg/ml) because TNF-α is involved in the pathogenesis of psoriasis." (PMID 29138509, 2017). "TNF-α is produced by e.g., dendritic cells, Th1-, Th22-, and Th17 cells, macrophages, and keratinocytes with multiple targets in psoriasis pathogenesis." (PMID 29104241, 2017). "They accepted the treatment of NB-UVB and the following data were collected: serum levels of IL-17 (interleukin), TNF-α (tumor necrosis factor) and IL-6, Psoriasis Area and Severity Index (PASI) scores before and after 10 sections of NB-UVB treatment." (PMID 29390261, 2017). "Excessive proinflammatory cytokines, such as TNF-α and IL-6, play a key role in the pathogenesis and progress of psoriasis." (PMID 29358932, 2017). "Downregulation of miR-125b has been observed in the lesional skin of patients with psoriasis and is negatively correlated with expression levels of fibroblast growth factor receptor 2 and TNF-α." (PMID 29232931, 2017). "Specifically, psoriasis and metabolic syndrome display similar inflammatory profiles with Th1 and Th17 T-cells as well as overexpression of cytokines such as IL-6 and TNF-alpha." (PMID 28719618, 2017). "Targeting the VN opens new therapeutic avenues in GI inflammatory diseases such as IBD, POI, IBS, and other TNFα-mediated diseases such as RA or psoriasis." (PMID 29163522, 2017). "The incidence of psoriasis during anti-TNF treatment for various clinical conditions has been estimated at 0.6–5.3%, and at 1.6–2% in patients who received anti-TNF agents due to IBD." (PMID 28905102, 2017). "Prolonged anti-TNF-α therapy has beneficial effects on the signs of subclinical cardiovascular disease in patients with severe psoriasis." (PMID 29348768, 2017). "Herein, we have shown increased expression of transcripts for TNF-α, of which the involvement in psoriasis is well-established, as well as CCL20 and hBD2, which are known to activate Th17 chemotaxis through CCR6." (PMID 28708859, 2017). "We next analyzed the mRNA expression of IFN-γ and TNF-α and their receptors in psoriasis skin and atherosclerotic tissue." (PMID 29062018, 2017). "Among various molecules, the major cytokines that are concurrently expressed in both adipose tissue and skin of patients with psoriasis are IL-6 and TNF-α." (PMID 29232931, 2017). "We demonstrated the anti-inflammatory functions and proposed the mechanisms for the amelioration of psoriasis-like symptoms by PAMs both in TNF-α/IFN-γ-induced HaCaT cells and imiquimod-induced psoriasis-like mouse." (PMID 28464025, 2017). "The prevalence of LTBI varies according to countries, and was 12/110 (11%) and 10/101 (10%) in Taiwan among TNF-blockers users for psoriasis." (PMID 28886099, 2017). "For example, TNF-alpha, which is overexpressed in patients with psoriasis, is also elevated with abdominal obesity, a component of metabolic syndrome." (PMID 28719618, 2017). "The immunological component of psoriasis is marked by high levels of pro-inflammatory cytokines and chemokines, including interferon-γ, interleukins 1, 6, 17, and 22 and tumor necrosis factor (TNF)α64–69." (PMID 28928444, 2017). "Although the role of Th1 cells in psoriasis is questioned, the use of cytokine antibodies in treatments has shown that IL-23, TNF, and IL-17 play key roles in the pathogenesis of psoriasis." (PMID 29292715, 2017). "This correlated with a retrospective study on patients with psoriasis treated with a TNF-α inhibitor or ustekinumab, that demonstrated longer drug survival and the lowest proportion of loss of efficacy for ustekinumab compared with the TNF-α inhibitors." (PMID 29104241, 2017). "Both psoriasis and IBD are Th1-mediated inflammatory disorders associated with enhanced synthesis of cytokines, TNF-alpha and interferon-gamma (IFN-gamma)." (PMID 28905102, 2017).